DDX3X (DEAD-box helicase 3 X-linked)
Diseases named in the same sentence as DDX3X in open-access papers (continued):
Sharing a sentence is not in itself a finding about the gene and the disease.
lung carcinoma (continued). "The role of DDX3X in lung cancer is still contradictory; in fact, in lung cancer cells, DDX3X was found overexpressed and was associated with short patient survival." (PMID 35954483, 2022). "Consistent with the findings in lung cancer, DDX3X is also upregulated in cisplatin-resistant oral squamous cell carcinoma (OSCC) cells compared to cisplatin-sensitive OSCC cells." (PMID 33627125, 2021). "Either ligand-independent or ligand-induced EGFR phosphorylation was inhibited in lung cancer cells that strongly expressed DDX3X." (PMID 25343452, 2014). "In this study, we investigated the role of DDX3X in acquisition of EGFR-TKI resistance in lung cancer cells." (PMID 25343452, 2014). "In this study, we sought to investigate the role of DDX3X in conferring EGFR-TKI resistance in lung cancer cells." (PMID 25343452, 2014). "This discovery establishes a direct link between DDX3X, metabolism, and cell death in lung cancer." (PMID 40885716, 2025). "In addition, we showed that J10 efficiently degraded DDX3X in all 6 lung cancer cell lines tested in this study." (PMID 40885716, 2025). "In our pursuit of evaluating DDX3X as a therapeutic target in lung cancer, we conceived twelve potential heterobifunctional DDX3X degraders using Proteolysis Targeting Chimeras (PROTACs) technology, which leverage the ubiquitin-proteasome system to induce DDX3X degradation." (PMID 40885716, 2025). "Our data indicated that patients with higher expression of DDX3X/CBS, DDX3X/METTL16 and DDX3X/JUND exhibited poorer overall survival and progression-free interval, suggesting the prognostic value of DDX3X and its associated genes for lung cancer patients." (PMID 40885716, 2025). "Specifically, our study focuses on how DDX3X regulates lung cancer metabolism." (PMID 40885716, 2025). "Indeed, using different lung cancer models, we demonstrated that the DDX3X degrader J10 efficiently induces DDX3X degradation and exhibits significantly more anti-tumor effects in all in vivo models with less toxicity compared to RK-33." (PMID 40885716, 2025). "Additionally, we have developed novel DDX3X PROTAC degraders and compared their anti-tumor efficiency with RK-33, showcasing their great potential and advantages in targeting DDX3X for lung cancer therapeutics." (PMID 40885716, 2025). "There are researches revealed that DDX5 and DDX3X were identified as regulators in lung cancer." (PMID 35864588, 2022). "In lung cancer, both DDX3X and DDX5 have been found to physically interact with the oncogene MATR3." (PMID 35954483, 2022). "Moreover, direct modulation of DDX3X to Slug/E-cadherin signaling axis has been shown to repress invasion in lung cancer." (PMID 31906196, 2019).
lung carcinoma (continued). "Our results showed that inhibition of DDX3X may be a promising therapy for overcoming primary EGFR-TKI-resistance mechanisms based on intratumor heterogeneity and for achieving a cure in lung cancer patients harboring EGFR-activating mutations." (PMID 25343452, 2014). "Furthermore, the levels of malondialdehyde (MDA) and 4-hydroxynonenal (4-HNE), both markers of oxidative stress-induced lipid peroxidation and ferroptosis, were significantly elevated in shDDX3X cells, indicating that DDX3X ablation instigates ferroptotic cell death in lung cancer cells." (PMID 40885716, 2025). "In conclusion, our findings elucidate the critical function of DDX3X in maintaining antioxidant homeostasis and provide an alternative strategy to treat KRAS-driven lung cancer." (PMID 40885716, 2025). "Given DDX3X role as a crucial RNA-binding protein governing various aspects of gene expression, our study in KRAS-driven lung cancer cells revealed that DDX3X influences CBS translation without affecting transcription or mRNA stability." (PMID 40885716, 2025). "Among them, lung cancer, gallbladder carcinoma and the smoking subpopulation of patients with HNSSC shows a correlation between overexpression of DDX3X and poor prognosis (overall survival (OS)/relapse-free survival (RFS)/median survival time)." (PMID 33627125, 2021). "Taken together, our current data and these previous studies indicate that DDX3X is a critical component of the Wnt/β-catenin signaling pathway and that signal switching from EGFR addiction to β-catenin signaling could be induced by DDX3X in lung cancer cells harboring EGFR-activating mutations." (PMID 25343452, 2014). "Furthermore, we demonstrated that METTL16-dependent m6A modification is essential for DDX3X-regulated CBS expression and lung cancer proliferation." (PMID 40885716, 2025). "Finally, by performing co-immunoprecipitation and immunofluorescence assay, we excluded the possibility of direct interaction between DDX3X and JUND in lung cancer cells." (PMID 40885716, 2025). "Given that JUND is a transcription factor in lung cancer progression, we further investigated whether JUND acts as a nexus between METTL16 and DDX3X." (PMID 40885716, 2025). "While previous studies have highlighted the significance of DDX3X in lung cancer progression, and small molecule inhibitors such as RK-33 have been developed for treating lung cancer, no clinical trials involving DDX3X inhibitors have been initiated thus far." (PMID 40885716, 2025). "While our investigation highlights one mechanism by which DDX3X regulates lung cancer progression, it does not preclude the existence of other potential roles of DDX3X in tumorigenesis." (PMID 40885716, 2025). "Low expression of DDX3X is correlated with poor prognosis in lung cancer, CRC and the non-smoking subpopulation of patients with HNSSC." (PMID 33627125, 2021). "Conversely, a reduction in DDX3X has been reported in HNSSC, lung cancer, HCC, and CRC." (PMID 33627125, 2021). "Lung cancer cells harboring EGFR exon 19 deletion and DDX3X cDNA have been observed to have reduced EGFR-tyrosine kinase inhibitor (TKI) sensitivity and cancer stem cell phenotypes, suggesting a role for DDX3X in drug resistance acquisition." (PMID 31906196, 2019).
hepatocellular carcinoma (35 papers, 2010 to 2025). A malignant tumor that arises from hepatocytes. "Other studies revealed the loss of DDX3X expression in hepatocellular carcinoma tissue, and increased tumor cell proliferation because of the DDX3X silencing in hepatocellular carcinomas which were infected by hepatitis virus." (PMID 37371098, 2023). "DDX3X knockdown was further proved to induce cancer cell proliferation in hepatitis virus-associated hepatocellular carcinoma." (PMID 32326089, 2020). "The antitumor activity of rottlerin in hepatocellular carcinoma cells has been suggested to occur in a DDX3X-dependent manner that causes cell cycle arrest in the G1 phase." (PMID 31906196, 2019). "In this research study, I first observed the potentially therapeutic application of chaetocin for hepatocellular carcinoma in terms of precision medicine; that is, especially for those cancer patients displaying high DDX3X expression levels." (PMID 37371098, 2023). "In this study, I first aimed to characterize DDX3X’s role from the perspective of its prognostic significance in hepatoma patient survival." (PMID 37371098, 2023). "Lentiviral-based silencing of DDX3X in a hepatocellular carcinoma (HCC) cell line resulted in the suppression of cell migration and invasion." (PMID 37371098, 2023). "In this study, I characterized DDX3X’s clinical significance in predicting poor hepatoma patient survival based on RNA expression data." (PMID 37371098, 2023). "High DDX3X expression levels were detected in hepatocellular carcinoma to promote hepatocarcinogenesis." (PMID 32326089, 2020). "On the other hand, the tumor suppressor role of DDX3X has been characterized: silencing of DDX3X expression in hepatocellular carcinoma HepG2 cells promoted chemoresistance to anti-cancer drugs doxorubicin and 5-fluorouracil." (PMID 31906196, 2019). "While the role of DDX3X in hepatocellular carcinoma is mainly as a tumor suppressor, its involvement in ovarian cancer is still unknown." (PMID 35954483, 2022). "Our study corroborated these findings, confirming that DDX3X promotes both proliferation and metastasis of hepatocellular carcinoma (HCC) in both in vivo and in vitro models." (PMID 41198618, 2025). "The overexpression of ATP-dependent RNA helicase DDX3X has been detected in hepatocellular carcinoma (HCC), and ATP-dependent RNA helicase DDX3X has been characterized as a critical gene in hepatocarcinogenesis." (PMID 37371098, 2023). "The DDX3X protein is stabilized by TCEA1, which promotes hepatocellular carcinoma cell proliferation and colony formation." (PMID 31906196, 2019). "In contrast, lower DDX3X was shown in hepatocellular carcinoma tissue, which was compared with adjacent non-tumor tissue." (PMID 32326089, 2020). "In contrast, DDX3X is downregulated in hepatocellular carcinoma tissue compared to paired adjacent non-tumor tissues." (PMID 26184164, 2015). "DDX3X overexpression was found in hepatocellular carcinoma (HCC) cells; however, while an oncogenic role of DDX3X in HCC has never been clearly demonstrated, several studies proposed a molecular mechanism that supports an oncosuppressive role of DDX3X." (PMID 35954483, 2022).
Intellectual disability (35 papers, 2016 to 2025). "Heterozygous de novo variants in DDX3X cause DDX3X syndrome and are associated with both monogenic intellectual disability and autism." (PMID 41312597, 2025). "DDX3X-related neurodevelopmental disorder is one of the most common monogenic causes of intellectual disability in females, with currently >1000 females diagnosed worldwide." (PMID 40164730, 2025). "Germline variants in DDX3X are one of the most common causes for intellectual disability in females; indeed more than a hundred affected individuals have been reported." (PMID 39149612, 2024). "For instance, de novo variants in DDX3X are associated with severe NDD, structural brain abnormalities, and intellectual disability, while somatic DDX3X variants are associated with aggressive cancers." (PMID 39736890, 2024). "Among these, DDX3X, regulates gene splicing and is associated with neurodevelopmental disorders characterised by intellectual disability, ASD and more recently, CAS." (PMID 36117209, 2023). "Secondly, mutations in DDX3X cause neurodevelopmental abnormalities in females, including intellectual disability, cortical malformations, autism and epilepsy." (PMID 37672513, 2023). "DDX3X variants are a common cause of intellectual disability (ID) in females, and have been associated with autism spectrum disorder and emotional-behavioural difficulties." (PMID 35536379, 2023). "De novo DDX3X variants account for 1–3% of unexplained intellectual disability cases in females and very rarely in males." (PMID 35392274, 2022). "Mutations in the RNA helicase, DDX3X, are a leading cause of Intellectual Disability and present as DDX3X syndrome, a neurodevelopmental disorder associated with cortical malformations and autism." (PMID 35762573, 2022). "A total of 23 Chinese patients (i.e., 22 female and 1 male) with 22 de novo DDX3X deleterious variants were detected among 2,317 probands with unexplained intellectual disability (ID) undertaking whole exome sequencing (WES)." (PMID 35392274, 2022). "About 1–3% of females with unexplained intellectual disability (ID) carry de novo pathogenic variants in the X-linked DDX3X gene (Xp11.4)." (PMID 33789733, 2021). "De novo genetic variants in DDX3X cause developmental delay and intellectual disability in DDX3X-syndrome." (PMID 33905506, 2021). "Heterozygous missense or loss-of-function mutations in DDX3X are also implicated in intellectual disability and autism-spectrum disorders in females, with the severity of phenotype correlating with the degree of reduction in DDX3X catalytic activity." (PMID 34535544, 2021). "De novo pathogenic variants in the DDX3X gene are reported to account for 1–3% of unexplained intellectual disability (ID) in females, leading to the rare disease known as DDX3X syndrome (MRXSSB, OMIM #300958)." (PMID 33789733, 2021). "De novo DDX3X variants account for 1%-3% of intellectual disability (ID) in females and have been occasionally reported in males." (PMID 32714884, 2020). "Amongst the OGT and OGA correlated genes implicated in cell cycle regulation, the gene encoding the RNA helicase DDX3X, an RNA helicase linked to S-phase entry and intellectual disability, was among the strongest OGT/OGA correlated genes (r = 0.68 and r = 0.74, respectively)." (PMID 40592469, 2025). "A pathologic variant in DDX3X was found through an intellectual disabilities WES panel." (PMID 40822950, 2025). "Nevertheless, it is unclear how the role of DDX3X in Wnt signaling may contribute to the development of intellectual disability in carriers of pathogenic variants." (PMID 39149612, 2024). "Additionally, thirty-five de novo variants were identified in the DDX3X gene in females with intellectual disability, along with additional features such as hypotonia, movement disorders, behavioral problems, corpus callosum hypoplasia, and epilepsy." (PMID 39768765, 2024). "Similar to ADHD, mutations in DDX3X have been associated with intellectual disability." (PMID 37953273, 2023).
Intellectual disability (continued). "These multiple links to translation of mRNAs for neurodevelopmental genes may provide insights into the causes of DDX3X-associated intellectual disability (DDX3X syndrome)." (PMID 36393867, 2022). "A range of de novo germline DDX3X mutations can cause ‘DDX3X syndrome’, a neurodevelopmental condition presenting with intellectual disability, microcephaly, and other symptoms, which may be attributed at least in part to altered translational regulation." (PMID 36393867, 2022). "For example, mutations in DDX3X, one of the PTCHD1-specific interactors, disrupt RNA metabolism, induce neuronal RNA granule formation, and lead to intellectual disability." (PMID 36769003, 2023). "We confirmed the importance of DDX3X as a pathogenic gene in unexplained intellectual disability, supporting the necessity of the application of WES in patients with unexplained intellectual disability." (PMID 35392274, 2022). "Mutations in DDX3X are associated with lymphocytic leukemias, WNT signaling and and intellectual disability." (PMID 26934103, 2016). "Moreover, it is striking that mutations in other DEAD box RNA helicases, such as DHX30, DDX3X, or DDX59, all cause intellectual disability or other neurodevelopmental disorders." (PMID 38536035, 2024). "Interestingly, its paralog DDX3X, is listed as strong ASD candidate (category 2) in the SFARI autism gene database and has been associated with cases of intellectual disability, hyperactivity, and aggression in females." (PMID 32012899, 2020). "In parallel, we noted that deletion of the CTE segregated with microcephaly and intellectual disability, and truncation of the CTE was reported to attenuate DDX3X RNA helicase activity in a separate study." (PMID 40592469, 2025). "Fourth, the candidate genes newly implicated in CAS were frequently associated with other neurodevelopmental disorders, such as epilepsy (e.g. GNAO1, GNB1, SETD1A) and/or intellectual disability (e.g. CDK13, CHD3, DDX3X, POGZ, SETBP1)." (PMID 36117209, 2023). "Skewed XCI of the XCI-escaping genes DDX3X and SMC1A were revealed in intellectual disability female patients." (PMID 31781162, 2019). "Of note, most individuals with variants in DDX3X, KAT6A, and DYRK1A have moderate‐to‐severe intellectual disability and do not typically use verbal speech to communicate." (PMID 39846212, 2025).